ZNF136 (zinc finger protein 136)
Description:
May be involved in transcriptional regulation as a weak repressor when alone, or a potent one when fused with a heterologous protein containing a KRAB B-domain.
Synonyms: pHZ-20
Tractability: PROTAC: ubiquitination databases record sites on it.
Gene: Protein-coding gene on chromosome 19 (12,163,064 to 12,189,871, forward strand). Ensembl gene ENSG00000196646.
Subcellular location: Nucleus
Subcellular location (Human Protein Atlas): Nucleoli
Pathways (Reactome):
Gene expression (Transcription): Generic Transcription Pathway; Regulation of endogenous retroelements by KRAB-ZFP proteins
Gene Ontology:
Molecular function: protein binding; DNA-binding transcription factor activity, RNA polymerase II-specific; RNA polymerase II cis-regulatory region sequence-specific DNA binding
Biological process: negative regulation of transcription by RNA polymerase II; regulation of transcription by RNA polymerase II; regulation of DNA-templated transcription
Cellular component: nucleus
Genetic constraint (gnomAD): Loss-of-function variants: 10 observed, 11.5 expected, observed/expected ratio (o/e) 0.87, 90% interval 0.54 to 1.47. The upper end of that interval is the gene's LOEUF score, 1.47, which puts it in group 6 of 6, group 1 being the genes least tolerant of losing a copy. Missense variants: 590 observed, 687.86 expected, observed/expected ratio (o/e) 0.86, 90% interval 0.8 to 0.92. Synonymous variants: 190 observed, 214.65 expected, observed/expected ratio (o/e) 0.89, 90% interval 0.79 to 1.
Homologues: Orthologues: chimpanzee ZNF136 (99% identical), macaque ZNF136 (98% identical). Paralogues in human: ZNF627 (59% identical), ZNF625 (44% identical), ZNF670 (43% identical), ZNF527 (38% identical), ZKSCAN7 (37% identical), ZNF852 (36% identical), ZNF426 (35% identical), ZNF287 (35% identical), ZNF34 (35% identical), ZNF17 (34% identical), ZNF285 (34% identical), ZNF214 (34% identical), and 38 more.
Diseases named in the same sentence as ZNF136 in open-access papers:
ZNF136 is named in the same sentence as 4 diseases in open-access papers, as found by Europe PMC text mining. Sharing a sentence is not in itself a finding about the gene and the disease. The quoted sentences say what the papers report.
chronic kidney disease (1 paper, 2023). Impairment of the renal function secondary to chronic kidney damage persisting for three or more months. "The ZNF136 gene is highly expressed in the kidneys, and encodes a protein that contains a Krüppel-associated box (KRAB) A-box domain, which has been associated to the development of progressive chronic kidney disease (CKD)." (PMID 37033211, 2023).
diabetic nephropathy (1 paper, 2023). "The genes that contributed to the biological relevance of diabetic nephropathy, include gene TTN (rs72646845), PI16 (rs113848006), DPY6 (rs36027551), CROCC (rs41272737), PPP1R3A (rs1799999), ZNF136 (rs140861589), HSPA12B (rs6076550), and FRMD4A (rs1541010)." (PMID 37033211, 2023).
schizophrenia (1 paper, 2025). A major psychotic disorder characterized by abnormalities in the perception or expression of reality. "We identify associations for STAG1 and ZNF136 at exome-wide significance, genes that were previously implicated in schizophrenia by the SCHEMA study at a false discovery rate of 5%." (PMID 40753099, 2025). "Both STAG1 and ZNF136 were previously implicated in schizophrenia by the SCHEMA study at FDR < 5%12, with further support for these associations now provided in the new case-control sample." (PMID 40753099, 2025). "Small-scale transcriptomic studies suggest that ZNF136 is downregulated in schizophrenia, but the mechanisms by which PTVs in ZNF136 may increase risk for schizophrenia are unclear." (PMID 40753099, 2025). "In conclusion, our study implicates STAG1 and ZNF136 in schizophrenia with exome-wide significance and 6 additional genes at FDR < 5%." (PMID 40753099, 2025). "We also found that rare PTVs in ZNF136 are enriched in schizophrenia at exome-wide significance." (PMID 40753099, 2025).
tumor (1 paper, 2022). "The tumor suppressive partners comprise three highly significant binding components: MIR99AHGlncRNA/PIK3R3, miR-661/ZYG11A, and PPP2R2B/ZNF136 (Supplementary Excel Files S4 and S5)." (PMID 36289596, 2022).